TRARG1 (trafficking regulator of GLUT4 (SLC2A4) 1 (gene/pseudogene))
Description:
Regulates insulin-mediated adipose tissue glucose uptake and transport by modulation of SLC2A4 recycling. Not required for SLC2A4 membrane fusion upon an initial stimulus, but rather is necessary for proper protein recycling during prolonged insulin stimulation.
Synonyms: DSPB1; IFITMD3; LOST1; TUSC5; BEC-1
Tractability: Antibody: UniProt places it where antibodies can reach, with medium confidence; UniProt predicts a signal peptide or a membrane-spanning region; its Gene Ontology location is reachable by antibodies, with medium confidence.
Gene: Protein-coding gene on chromosome 17 (1,279,662 to 1,300,978, forward strand). Ensembl gene ENSG00000184811.
Subcellular location: Cell membrane; Endomembrane system; Cytoplasm, perinuclear region
Gene Ontology:
Biological process: cellular response to insulin stimulus; endosome to plasma membrane protein transport; glucose import in response to insulin stimulus; protein localization to plasma membrane
Cellular component: cytoplasmic vesicle membrane; endomembrane system; plasma membrane; membrane; perinuclear region of cytoplasm
Genetic constraint (gnomAD): Loss-of-function variants: 16 observed, 12.81 expected, observed/expected ratio (o/e) 1.25, 90% interval 0.84 to 1.81. The upper end of that interval is the gene's LOEUF score, 1.81, which puts it in group 6 of 6, group 1 being the genes least tolerant of losing a copy. Missense variants: 237 observed, 237.1 expected, observed/expected ratio (o/e) 1, 90% interval 0.9 to 1.11. Synonymous variants: 110 observed, 107.34 expected, observed/expected ratio (o/e) 1.02, 90% interval 0.88 to 1.2.
Homologues: Orthologues: chimpanzee TRARG1 (95% identical), macaque TRARG1 (88% identical), dog TRARG1 (76% identical), rabbit TRARG1 (76% identical), mouse Trarg1 (74% identical), guinea pig TRARG1 (71% identical), pig TRARG1 (69% identical), rat Trarg1 (58% identical), tropical clawed frog trarg1 (47% identical), zebrafish trarg1a (44% identical), zebrafish trarg1b (31% identical). Paralogues in human: PRRT2 (33% identical), TMEM233 (23% identical), PRRT1B (18% identical), PRRT1 (17% identical).
Diseases named in the same sentence as TRARG1 in open-access papers:
TRARG1 is named in the same sentence as 12 diseases in open-access papers, as found by Europe PMC text mining. Sharing a sentence is not in itself a finding about the gene and the disease. The quoted sentences say what the papers report.
diabetes (1 paper, 2022). "TRARG1 is a member of the glucose transporter family and plays an important role in glucose transport, diabetes and insulin response." (PMID 35647086, 2022).
TRARG1 also shares sentences with these, for which no sentence is quoted: Insulin resistance (3 papers); tumor (3); cancer (2); lung carcinoma (2); osteosarcoma (2); adrenocortical tumors (1); breast carcinoma (1); hepatocellular carcinoma (1); mental retardation (1); Obesity (1); type 2 diabetics (1).